PRC1 (protein regulator of cytokinesis 1)
Diseases named in the same sentence as PRC1 in open-access papers (continued):
Sharing a sentence is not in itself a finding about the gene and the disease.
colon cancer (6 papers, 2020 to 2025). "We confirmed that PRC1 was overexpressed in colon cancer and was associated with poor prognosis of colon cancer patients." (PMID 33292244, 2020). "PRC1 expression was associated with clinicopathological characteristics and overall survival of patients with colon cancer." (PMID 33292244, 2020). "Our data presented in this study showed that PRC1 was overexpressed in colon cancer and was associated with poor OS." (PMID 33292244, 2020). "Our findings demonstrated the involvement of PRC1 in colon cancer, and highlighted its potential as a diagnostic, therapeutic, and prognostic maker for colon cancer." (PMID 33292244, 2020). "We show that one of the important epigenetic markers, H2AK119ub is regulated by SET/TAF-Iβ-MIB1 ubiquitinating complex in various cancers including colon cancer in PRC1-independent mechanism." (PMID 37746636, 2023). "The mRNA and protein expression levels of PRC1 were highly expressed in colon cancer tissues and cell lines." (PMID 33292244, 2020). "Here, we aimed to investigate the biological functions and potential mechanism of PRC1 in colon cancer." (PMID 33292244, 2020). "In this study, we sought to analyze the expression profile of PRC1 in colon cancer as well as the potential affinity between PRC1 and cancer prognosis." (PMID 33292244, 2020). "The data of Sabates-Bellver colon, Hong colorectal, and Skrzypczak colorectal showed that PRC1 was overexpressed in colon cancer compared to normal tissues." (PMID 33292244, 2020). "Then, PRC1 expression level was examined in 40 colon cancer tissues and paired adjacent normal tissues by qRT-PCR." (PMID 33292244, 2020). "The expression level of PRC1 in colon cancer tissues and cell lines was detected by quantitative real-time polymerase chain reaction (qRT-PCR), Western blotting, and immunohistochemical (IHC) staining of a tissue microarray (TMA)." (PMID 33292244, 2020). "Compared with the normal tissues, the PRC1 protein expression level was significantly elevated in colon cancer tissues (P < 0.001)." (PMID 33292244, 2020). "Kaplan–Meier survival analysis revealed that colon cancer patients with high expression level of PRC1 had a poorer overall survival (OS)." (PMID 33292244, 2020). "In the subsequent research, we will further reveal the potential regulation pathways for PRC1 in colon cancer." (PMID 33292244, 2020). "In order to further explore the expression pattern of PRC1 in colon cancer, we conducted IHC in an established TMA, which composed of 90 paired colon cancer tissues and neighboring non-cancerous tissues." (PMID 33292244, 2020). "Results from TMA suggested that the protein level of PRC1 was universally higher expressed in colon cancer tissues relative to the adjacent normal tissues (P < 0.001)." (PMID 33292244, 2020). "PRC1 plays an important role in the pathogenesis of various cancers, including colon cancer." (PMID 38168324, 2023). "Subsequently, we explored the effect of PRC1 on the cell cycle and apoptosis of colon cancer cells." (PMID 33292244, 2020). "Furthermore, the biological function of PRC1 was investigated in vitro and in vivo, and results showed that knockdown of PRC1 inhibited proliferation and promoted apoptosis of colon cancer cells." (PMID 33292244, 2020). "Given these confirmations of PRC1 functioning in cancer disease, it is unclear whether PRC1 operates in colon cancer." (PMID 33292244, 2020). "The present study depicted the correlation of colon cancer progress to PRC1 overexpression." (PMID 33292244, 2020). "Knockdown of PRC1 could decrease proliferation and colony forming ability of colon cancer cells, as well as arrested more cells at G2/M phase and promoted cell apoptosis." (PMID 33292244, 2020). "Here, we investigated whether protein regulator of cytokinesis (PRC1) might function as the diagnosis and prognosis of colon and whether showed a potential in targeted treatments of colon cancer." (PMID 33292244, 2020).
colon cancer (continued). "Additionally, cox regression analysis confirmed that PRC1 was an independent prognostic factor for colon cancer (95% CI: 1.840–12.346, P < 0.001)." (PMID 33292244, 2020). "Overall, these findings illustrated that inhibition of PRC1 could suppress colon tumor growth and differentiation." (PMID 33292244, 2020). "Most notably, our findings showed that silencing of PRC1 could significantly inhibit the proliferation and attenuate the colony forming ability of colon cancer cells." (PMID 33292244, 2020). "Next, we knocked down PRC1 to study its biological function in colon cancer." (PMID 33292244, 2020). "Moreover, we selected 12 pairs of colon tumor tissues and adjacent normal tissues to detect the expression of PRC1 protein." (PMID 33292244, 2020). "Meanwhile, its expression level was associated with the clinical indicators and OS of patients with colon cancer, revealing that PRC1 had carcinogenic effect and might be an ideal target for the therapy of colon cancer." (PMID 33292244, 2020). "Our data provided more evidence that PRC1 might serve a therapeutic target for colon cancer." (PMID 33292244, 2020). "Thus, we speculated that abnormal expression of PRC1 led to erroneous cell division, which in turn promoted the development of colon cancer." (PMID 33292244, 2020). "However, it is still unclear whether PRC1 shows similar expression profile and what roles PRC1 exactly plays in colon cancer." (PMID 33292244, 2020). "Together, our study reveals a novel PRC1-independent epigenetic regulatory mechanism for H2AK119ub by SET/TAF-Iβ and MIB1 in colon cancer." (PMID 37746636, 2023). "To explore the biological function of PRC1 in colon cancer cells, we established the colon cancer cells (SW480, HT-29, and HCT116) with lentivirus mediated PRC1 knockdown, which was validated by qRT-PCR and western blotting." (PMID 33292244, 2020). "Additionally, PRC1 down-regulation could suppress colon tumor growth and differentiation." (PMID 33292244, 2020). "Here, we showed that ZNF277 also interacts with BMI1 in human colon cancer cells, although the functional significance of this interaction and whether ZNF277 is a component of the PRC1 complex in intestinal epithelial cells remains to be determined." (PMID 35015732, 2022). "Furthermore, colon cancer cell lines HCT116 and SW480 were treated with short hairpin RNAs against PRC1." (PMID 33292244, 2020). "However, in colon cancer cells, it remains unclear whether KDM2B-induced EMT was dependent on its histone demethylase activity or PRC1 activity." (PMID 33779563, 2021). "Moreover, the precise pathway through which PRC1 influences colon cancer progression has not been explored." (PMID 33292244, 2020).
glioblastoma (6 papers, 2010 to 2025). The most malignant astrocytic tumor (WHO grade IV). "CBX7 is an important component of PRC1 and is involved in the development of various cancers, including glioblastoma." (PMID 39988672, 2025). "We show that CBX7 promotes the degradation of myosin heavy chain 9 (MYH9) protein through the ubiquitin-proteasome pathway via the polycomb repressive complex 1 (PRC1) and suppresses the stem-like phenotype of glioblastoma cells by inhibiting the nuclear factor kappa-B (NF-κB) signaling pathway." (PMID 39988672, 2025). "Here we reveal that CBX7, as part of the PRC1 complex, promotes MYH9 ubiquitination and degradation, thereby inhibiting the glioblastoma stem cell phenotype, with Ring1A/B serving as E3 ligases." (PMID 39988672, 2025). "Surprisingly, some PRC1 components (BMI1, CBX2, CBX7) were downreglated in glioblastoma compared to normal brain." (PMID 20920292, 2010). "Additionally, we have demonstrated for the first time that CBX7, as part of the PRC1 complex, promotes MYH9 ubiquitination and degradation, inhibiting stemness, migration, invasion, and colony formation in glioblastoma cells." (PMID 39988672, 2025). "Some specific pathways containing MELK have been identified in glioblastoma multiforme (GBM), such as the c-JUN/MELK and MELK/PRC1 cascades, which support the survival of cancer stem cells (CSCs)." (PMID 31861475, 2019).
glioma (6 papers, 2010 to 2022). A benign or malignant brain and spinal cord tumor that arises from glial cells (astrocytes, oligodendrocytes, ependymal cells). "Studies have demonstrated that SOX2-OT binds to nervous system polycomb 1 (NSPc1), a key component of polycomb repressive complex 1 (PRC1), in H4 glioma cells and U87 glioma cells, and regulates cancer cell proliferation and apoptosis." (PMID 33294436, 2020). "When the GPR17-silencing cells were treated with PRT4165, the ROS levels or the viable cell numbers returned to similar levels as those in U87/U251-shScr cells, suggesting that the inhibitory effect of GPR17 on glioma development was mediated by PRC1-mediated histone monoubiquitination." (PMID 34120140, 2021). "Even though the role of PRC1 in glioma mitosis and cytokinesis has not been investigated, data from the Human Protein Atlas indicates that there is a negative association of high expression levels of PRC1 and survival." (PMID 34885051, 2021). "Other PRC1 members (CBX7, PCGF6) were selectively expressed in lower grade gliomas." (PMID 20920292, 2010).
lymph node metastasis (6 papers, 2017 to 2025). "Further analysis of the correlations between these molecules and patient characteristics demonstrated that the staining intensities of phosphorylated PRC1 and CCNY were linked to advanced stages, lymph node metastasis, and distant metastasis in patients." (PMID 40665337, 2025). "The statistical analyses showed that high expression of PRC1 protein also significantly correlated with lymph node metastasis (P = 0.041) and p-TNM stages (P = 0.039)." (PMID 28646916, 2017). "Moreover, results showed that lymph node metastasis, p-TNM stages and PRC1 expression were significantly associated with OS (all P < 0.05)." (PMID 33292244, 2020). "Importantly, low levels of miR-1-3p and high levels of PRC1 were strongly associated with the TNM stage, lymph node metastasis, and distant metastasis." (PMID 30881920, 2019). "Concomitantly, PRC1 expression as determined using immunostaining in those patients with local lymph node metastasis or at stage T2 was stronger than those at T1 or having no metastasis (p < 0.05)." (PMID 29752448, 2018).
cervical carcinoma (5 papers, 2013 to 2025). A carcinoma arising from either the exocervical squamous epithelium or the endocervical glandular epithelium. "To date, few studies have reported the deregulation of components of PRC1 and their role in cervical cancer, with the exception of BMI1." (PMID 39793896, 2025). "In this study, via bioinformation analysis and immunohistochemistry (IHC), we found that chromobox 2 (CBX2), rather than other PRC1 components, was significantly upregulated in cervical cancer and was associated with poor prognosis." (PMID 39793896, 2025). "Hierarchical clustering and Gepia results indicated that the expression quantity of hub genes NDC80, TIPIN, MCM3, MCM6, POLA1, and PRC1 may determine the prognosis of cervical cancer." (PMID 33816217, 2021). "PRC1, CCNB2, and SYCP2 are markers exclusively associated with invasive cervical cancer." (PMID 23405241, 2013). "In this work we identified 6 genes (PRC1, CCNB2, SYCP2 CDKN3, NUSAP1, and CDC20) associated with invasive cervical cancer that could be used either as markers for diagnosis or as therapeutic targets." (PMID 23405241, 2013). "Of the top 10 ranked upregulated genes, 2 have not been previously reported as associated with cervical cancer (NUSAP1, and CDKN3), while the other 8 have been associated with cervical cancer either scantly (SYCP2, PRC1, CCNB2 and CDC20) or widely (MKI67, CDKN2A, CDC2, and PCNA)." (PMID 23405241, 2013). "To identify the PRC1 components that may play a role in cervical cancer, we used the The Cancer Genome Atlas (TCGA) and Genotype-Tissue Expression (GTEx) datasets to compare the transcriptional levels of PRC1 components in cervical cancers patients with those in normal controls." (PMID 39793896, 2025). "In conclusion, our results identified a deregulated PRC1 component, CBX2 and established an association between CBX2, tumor progression, and resistance to DNA damage treatment, providing some evidence for future targeted therapy against CBX2 in cervical cancer." (PMID 39793896, 2025). "Our data revealed a previously undescribed deregulated PRC1 component CBX2 in cervical cancer and showed that CBX2 plays a critical role in cervical cancer proliferation and resistance." (PMID 39793896, 2025). "Cell culture experiments suggest that expression of BMI1, a core component of PRC1, is reduced in E6/E7 transduced HFKs and BMI1 expression is inversely correlated with HPV titer in cervical carcinomas." (PMID 29069809, 2017).
Ewing sarcoma (5 papers, 2021 to 2025). A small round cell tumor that lacks morphologic, immunohistochemical, and electron microscopic evidence of neuroectodermal differentiation. "Our biogenic analysis further corroborates the close association between PRC1 and the PLK1 signaling pathway, aligning with findings from prior research on Ewing's sarcoma." (PMID 40093809, 2025). "Other than shaping the TME, we found that PRC1 was associated with the PLK1 pathway, which was in accordance with previous studies in Ewing sarcoma (EwS)." (PMID 35983074, 2022).
neuroblastoma (5 papers, 2015 to 2021). Neuroblastoma (NB) is the most common solid, extracranial childhood tumor. "In particular, genes associated with the maintenance of embryonic and adult stem cells, such as the components of PRC1 or PRC2, have been linked to the initiation and progression of neuroblastoma." (PMID 34638328, 2021). "Furthermore, we elucidated the upstream epigenetic repressive regulation of ELOVL2 through MYCN and PRC1 complex-mediated histone ubiquitination in MYCN-amplified neuroblastoma." (PMID 31856871, 2019). "For example, BMI1, a core component of the PRC1 complex, has been shown to cooperate in MYCN-driven neuroblastomas by inhibiting cell death and differentiation." (PMID 34638328, 2021). "In conclusion, MYCN recruits the PRC1 complex, co-occupies the ELOVL2 promoter, mediates H2AK119ub and suppresses its transcription in neuroblastoma cells." (PMID 31856871, 2019). "Although CHD5 has been shown to repress another PcG protein in neuroblastoma, BMI1 (a core component of PRC1), we did not observe an influence of CHD5 on BMI1 expression in HCC cells (data not shown)." (PMID 26517514, 2015).
synovial sarcoma (5 papers, 2012 to 2025). "Analysis of these SySa-selective dependencies using the STRING database showed enrichment in protein complexes involved in chromosome organization, WNT signaling, BAF complex, and PRC1 activity which are known dependencies in synovial sarcoma." (PMID 40804185, 2025). "This work further highlights the central role that PRC1 activity, and its derivate H2AK119ub1 histone mark, plays in driving and sustaining synovial sarcoma and supports inhibition of PRC1.1 as a potential therapeutic strategy." (PMID 37735617, 2023). "Furthermore, the C-terminal region of SSX confers preferential affinity to repressed, H2AK119Ub-marked nucleosomes, underlying the selective targeting to polycomb-marked genomic regions and synovial sarcoma–specific dependency on PRC1 function." (PMID 32747783, 2020). "The SS18-SSX fusion drives oncogenic transformation in synovial sarcoma by bridging SS18, a member of the mSWI/SNF (BAF) complex, to Polycomb repressive complex 1 (PRC1) target genes." (PMID 37735617, 2023). "Remarkably, the binding of PRC1 hinders the access of other chromatin remodeling complexes such as SWI/SNF that may have transcription-enhancing functions, which implies that out of the antagonistic partners of SYT-SSX in synovial sarcoma, CpG may ultimately dominate over SWI/SNF." (PMID 23110793, 2012).
uveal melanoma (5 papers, 2021 to 2023). A melanoma derived from melanocytes of the uveal tract. "Specifically, high-risk uveal melanoma cells exhibit low levels of H2AK119ub with nearly complete loss at PRC1 target loci when compared to low-risk uveal melanoma cells." (PMID 35954248, 2022). "Although the role of H2AK119ub in cutaneous melanoma is yet to be determined, the progression of uveal melanoma—a rare and deadly form of melanoma located at the ocular region, was recently reported to be driven by loss of PRC1 activity." (PMID 35954248, 2022). "Moreover, pharmacological inhibition of PRC1 catalysis in low-risk uveal melanoma resulted in acquisition of features related to high-risk cells, including the upregulation of genes associated with high-risk and poor prognosis." (PMID 35954248, 2022). "By integrating genetic, epigenetic, and functional analyses at the single cell level, we show that progression of uveal melanoma (UM), the most common intraocular primary cancer in adults, is driven by loss of Polycomb Repressive Complex 1 (PRC1) in a subpopulation of tumor cells." (PMID 34518527, 2021). "Changes in the chromatin landscape of tumor cells can often be triggered by a singular pathway or event such as inactivation of PRC1 activity in uveal melanoma." (PMID 36860651, 2023). "Pairwise comparisons of individual analyses (copy number, fragment size, fragment ratio, PRC1 fragment ratio, uveal melanoma methylation, liver methylation) showed variable correlations (R2 = −0.26 to 0.75) which suggests that each analysis may provide independent biological readouts." (PMID 36860651, 2023). "On the transcriptomic level, uveal melanoma progression and aggressiveness is driven by inactivation of both BAP1, a subunit of the polycomb-repressive deubiquitylase complex and polycomb repressive complex 1 (PRC1) activity, leading to derepression of PRC1 target genes." (PMID 36860651, 2023).
acute myeloid leukemia (4 papers, 2022 to 2025). Acute myeloid leukemia (AML) is a group of neoplasms arising from precursor cells committed to the myeloid cell-line differentiation. "Dysregulation of the menin-KMT2A and polycomb repressive (PRC1/2) complexes in MLL-rearranged and NPM1-mutated acute myeloid leukemia (AML) contributes to the aberrant expression of self-renewal genes in hematopoietic stem and progenitor cells." (PMID 39607901, 2025). "The current work aimed to examine the role of PRC1 in acute myeloid leukemia (AML) and to assess the impact of BKT300, a small molecule PRC1 inhibitor, on AML cell viability and tumor growth in mouse xenograft AML models." (PMID 40034437, 2025). "Noncanonical PRC1 complex member BCOR is ubiquitously expressed across adult tissues, and mutations within this gene occur in acute myeloid leukemia (AML), myelodysplastic syndrome (MDS), chronic myelomonocytic leukemia (CMML), and aplastic anemia." (PMID 38028538, 2023).
Cirrhosis (4 papers, 2019 to 2022). A chronic disorder of the liver in which liver tissue becomes scarred and is partially replaced by regenerative nodules and fibrotic tissue resulting in loss of liver function. "Hence, TOP2A, PRC1, and NUSAP1 have the potential to be liver biopsy-based markers for screening HCC high-risk patients with cirrhosis." (PMID 31001331, 2019). "This study revealed that PRC1, RACGAP1, CENPF, and CCNB2 could sensitively distinguish HCCfrom cirrhosis, and they may be potential targets for early HCC detection." (PMID 35445033, 2022). "PRC1, RACGAP1, and CDCA5 were identified as the crucial genes in the pathological progression from cirrhosis to HCC, and their hypomethylation may drive the high expression of these genes." (PMID 33505422, 2020).